MYCN (MYCN proto-oncogene, bHLH transcription factor)
Diseases named in the same sentence as MYCN in open-access papers (continued):
Sharing a sentence is not in itself a finding about the gene and the disease.
cancer (continued). "MF HSC/MPP showed a high expression of immune and inflammatory pathways (HLA genes, GBP4, and IFITM1), a matrix- and collagen-degrading enzyme (MMP2), and genes with oncogenic function (MYCN, KRT8, and KRT18) that have been correlated with cancer progression and poor survival." (PMID 34525349, 2021). "Gene amplification is the most commonly observed alteration in cancer for the MYC gene family, and MYCN amplification is found particularly in NB in about 25% of diagnosed cases and is strongly associated with poor prognosis, thereby being a defining feature of high-risk NB." (PMID 34771690, 2021). "MYC proteins regulate a range of cellular processes and their dysregulation has a large impact on the development of cancer: different types of MYC and MYCN alterations have been identified in a large variety of cancers and they are often correlated with poor prognosis and reduced survival." (PMID 34689785, 2021). "Despite considerable analysis carried out in this study on the ALYREF and MYCN regulatory circuit, it is not yet fully clear how MYCN-promoted oncogenic levels of ALYREF reprogram cells to help the cancer state." (PMID 33767157, 2021). "I-type cells were shown to be significantly more malignant than N- or S-type NB independent of MYCN amplification and suggested as cancer stem cell population according to their CD133 positive background." (PMID 34026614, 2021). "The minimal or lack of activity of these compounds in non-malignant cells and in cancer cells with wild type KRas and low levels of MYCN is a promising feature for the development of novel therapies." (PMID 33287862, 2020). "Unlike non-amplified cells, MYCN-amplified cancer cells significantly promote OXPHOS-dependent ATP synthesis." (PMID 32547946, 2020). "Cancer cells isolated by the sphere formation assay displayed self‐renewal properties, upregulation of EMT markers (vimentin, Snail/Slug and N‐cadherin), stemness and developmental genes (CD105, CD133, CXCR4, NANOG, MYCN, and WNT)." (PMID 30883740, 2019). "The MYC family oncogenes (MYC, MYCN, and MYCL) contribute to the genesis of many human cancers." (PMID 31452837, 2019). "The MYC proto-oncogenes (MYC, MYCN, MYCL) have been extensively studied since their discovery in the early 1980’s and they continue to be of great interest as the most commonly deregulated genes in human cancer." (PMID 29799508, 2018). "Interestingly, we also show that seven major gene regulators (TP73, RICTOR, NUPR1, NKX2‐3, MYCN, IL10, and EPO) involved in inflammation, oxidative stress, DNA damage, and cancer processes were affected by MP radiation." (PMID 29786969, 2018). "In addition, we found that SGO1 is a transcriptional target of MYCN, and that SGO1 expression correlates with MYCN or MYC expression in various cancers." (PMID 27539729, 2016). "In this study, we demonstrate that PlGF is up-regulated in NB tissue and serum of patients and provide experimental evidence for a cancer promoting activity of PlGF in MYCN-non-amplified NB." (PMID 27669225, 2016). "Our data support the existence of a regulatory circuit between MYCN and TFAP4, where TFAP4 is directly induced by MYCN, then cooperates with MYCN to regulate a subset of MYCN-target genes involved in cancer cell proliferation and metastasis, nucleotide and protein synthesis and growth." (PMID 27448979, 2016).
cancer (continued). "In addition, pan-aurora kinase inhibitors, VX-680 and CCT137690 which also target AURKB, were reported to sensitize cancer cells with high expression of MYC and MYCN." (PMID 26497213, 2015). "Clearly further studies on a wider set of MYCN/LSD1 common target genes will be instrumental to address these issues and to determine the exact molecular background in which the LSD1/MYCN complex operates inside cancer cells." (PMID 26062444, 2015). "In summary, the results of this study indicate a double advantage of the use of 2DG in treatment of mice loaded with either MYCN-amplified DZ cells or MYCN-non-amplified AS cells, by simultaneously targeting cancer cells and endothelial cells." (PMID 26398947, 2015). "We found that simultaneous targeting of cancer cells and endothelial cells by 2DG in vivo was responsible for successful suppression of the growth of NB, regardless of the status of MYCN amplification." (PMID 26398947, 2015). "Given the structural similarity and functional redundancy between MYCN and MYC, R9-caPep might be effective in treating cancers that overexpress MYC as well." (PMID 24728180, 2014). "The most intriguing finding of this study is that NB cells with MYCN amplification are more sensitive to R9-caPep treatment than NB cells without MYCN amplification, as MYCN-amplified NB cancers are characteristically aggressive and resistant to therapy." (PMID 24728180, 2014). "Examples of genes amplified on DMs include MYCN in neuroblastoma, C-MYC in colon cancer cells, EGFR in gliomas, and eIF-5A2 in ovarian cancer cells, and all of which when lost via DMs contributes to reversal of the cancer phenotype." (PMID 23991020, 2013). "Thus, MYCN behaves as an embryonal TAA whose expression is down-regulated shortly after birth and up-regulated in cancer cells of neuroectodermal origin, including NB, through different mechanisms such as gene amplification." (PMID 23162796, 2012). "Particularly MYCN was involved in the ERK/MAPK signaling pathway and cancer." (PMID 21595958, 2011). "If significant epigenetic and transcriptional regulation of amplified MYCN (implied by these studies) can be validated in primary tumors, these studies would support BMYB as target for therapeutic intervention in MYCN amplified cancers." (PMID 21304174, 2010). "Finally, we have identified a number of down-regulated miRNAs whose targets are up-regulated in cancer, including the oncogenic protein KRAS and MYCN, mitogen-activated protein (MAP) kinases and the anti-apoptotic proteins BCL2, BCL2L2 and MCL-1 among others." (PMID 20668671, 2010). "Despite these advances, effectively targeting MYCN remains a significant challenge due to its lack of a defined active site, intrinsically disordered regions, and the adaptability of transcriptional programs in cancer cells." (PMID 40027135, 2025). "Therefore, the results indicate that the anti-cancer effects of 248 and 249 are not influenced by MYCN gene amplification or the overexpression of the MYCN protein." (PMID 40243990, 2025). "Understanding how MYCN, can play an essential role in delineating ER stress responses and other metabolic changes within an NEPC cell could assist in effectively targeting NEPC cancers." (PMID 41198652, 2025). "Last, we evaluated whether the negative association between MYCN and IFN type I signatures extended to other cancer types." (PMID 38748789, 2024). "No DDX1 amplifications without MYCN were detectable in 556 cancer genomes." (PMID 38197697, 2024). "We hypothesize that MYCN mRNA molecules, despite their substantial production resulting from gene amplification in MYCN‐driven cancers, are not efficiently translated into proteins without the functional contribution of DDX3X." (PMID 37975412, 2024).
cancer (continued). "To test this hypothesis, we analyzed metabolomics data from the CCLE database including measurements of 225 metabolite levels in 928 cell lines from more than 20 cancer types and compared metabolite levels between cells with DDX1-MYCN coamplification to those only harboring MYCN amplification." (PMID 38197697, 2024). "These MYCN-absent regions clearly co-expressed the myofibroblast markers Tagln and Acta2, consistent with the idea that these mesenchymal cells are fibroblasts and not cancer cells." (PMID 38898465, 2024). "Currently, there is no treatment for targeting MYCN or MYC in cancer." (PMID 39101440, 2024). "Thus, the inhibition of MYCN represents a new relevant cancer treatment, specific for MYCN-driven human tumors, without affecting healthy cells." (PMID 36765949, 2023). "However, no studies have been conducted to analyze in depth the potential mechanisms by which MYCN affects the prognosis of ccRCC, so we do not yet know why MYCN plays a different role in ccRCC than in other cancers." (PMID 37213288, 2023). "Interestingly, when MYCN is high, the simple downregulation of RB1 is ineffective on cell growth or on reduction of cancer aggressiveness as implied by the Kaplan Meier graphs in which it is shown that E2F3 and MYCN expressions are strong prognostic markers of clinical outcome independently of RB1." (PMID 36982482, 2023). "It has been reported that the occurrence and development of cancer depends in part on the mechanism by which BRD4 can specifically recognize and anchor the side chain acetylated lysine on superenhancer open chromatin to promote the transcription of the MYCN gene." (PMID 36438198, 2022). "MYCN is amplified in some forms of neuroblastoma and prostate cancers and predicts poor prognosis; therefore, inhibition of AURKA–MYCN binding might also be a useful therapeutic approach in these cancers." (PMID 34944109, 2021). "Given the demonstrated oncogenic relevance of MYCN in many types of cancers, whether the PLAGL2-MYCN axis is also a key player in modulating cell differentiation and proliferation in other cancer types is certainly an interesting question to address in the future." (PMID 32087738, 2020). "Moreover, activation of several FGF downstream signaling pathways was also observed including cancer related pathways (RAS-MAPK, PIK3-AKT, and STAT) with a significant upregulation of several key molecules in these pathways (e.g., BIRC5, RAF1, MYCN, IGF2, SNAI2, POSTN)." (PMID 31477684, 2019). "Moreover, we found that MYCN mediated the folate cycle via MTHFD2, which contributed one-carbon unit to enhance purine synthesis, and further regulated nucleotide production by PAICS in response to cancer progression." (PMID 31624245, 2019). "MFHAS1, regulated by TF MYCN in our remission sub-network, may be a significant prognosis factor for AML in The Cancer Genome Atlas (TCGA) cohort and could promote the progress of cancer." (PMID 30195757, 2018). "Notably, MYCN-amplified UKF-NB-3 cells were found to be substantially more sensitive to influenza A virus-induced anti-cancer effects than MYCN-non-amplified SK-N-AS cells." (PMID 28192521, 2017).
cancer (continued). "To compare the MYCN-ER responsive genes and the steady state MYCN responsive genes with a current compilation of MYC targets in the MYC Target Gene database, we mapped MYCN responsive genes identified here, and those found in the MYC cancer database to UNIGENE cluster IDs." (PMID 19690609, 2009). "Additionally, the proto‐oncogene MYCN was upregulated together with SOX2 and YAP1, both markers for stem cell self‐renewal, reprogramming and homeostasis, as well as mechanistically promoting proliferation, survival, invasion/metastasis, cancer stemness and drug resistance." (PMID 36819185, 2023). "Importantly, among these markers, MYCN and CCT2 expression showed the highest t-values, indicating a distinct difference between the two sample types, which suggests that the difference in CCT2 gene expression between cancer and normal tissues is more likely to be true and reliable." (PMID 36185250, 2022). "Therefore, given that the movement of malignant cancer cells can be compared to that of migrant neutrophils the aim of this study was to analyze the biological effect of STIRUR 13, STIRUR 41 and BUR 12 on NB cell lines characterized by a different status of MYCN amplification." (PMID 32973970, 2020). "Finally, CNAtra successfully detected the previously-reported focal amplifications of MYC (NCI-H82) and MYCN (CHP-212, IMR-32) loci as well as homozygous focal deletions of BANK1/4q24 (NCI-H82), LKB1/STK11 (A427), and p16INK4a/CDKN2A (A427) loci in respective cancer cell lines." (PMID 32299346, 2020). "Therefore, the down-regulation of the MYCN-miR-17-92 network in order to increase the TRIM8 expression level in cancer cells represents an interesting approach to inhibit uncontrolled cell proliferation and tumour growth and sensitize cancer cells to chemo- and radiotherapy in vivo." (PMID 30974870, 2019). "As MYCN is an oncogenic driver in a wide variety of cancers, our findings highlight the importance of developing PRMT5 small molecule inhibitors for cancer therapeutics targeting MYCN; currently no specific inhibitors are available." (PMID 25475372, 2015). "Our results, highlighting differences in E-box selection between MYCN and c-MYC would indicate that these transcription factors should not be completely functionally redundant in cancer." (PMID 19997598, 2009). "Notably, sequence alignment did not reveal the S67 phosphorylation site in N-Myc, potentially explaining the non-regulatory role of Aurora B in MYCN-amplified cancers." (PMID 36902175, 2023). "Of note, the WDR5 or G9a dependency was not dependent on MYCN amplification status, which is possible due to the high expression of c-Myc in MYCN non-amplified NB cell lines, while WDR5 and G9a have been shown to mediate c-MYC function in the other types of cancers." (PMID 37781575, 2023). "However, the relevance of the MYCN → MDM2 axis in developing tumors, as opposed to immortalized cancer cell lines, had not been demonstrated." (PMID 33425720, 2020).
infection (18 papers, 2012 to 2025). The state of being infected such as from the introduction of a foreign agent such as serum, vaccine, antigenic substance or organism. "The conclusion is that MYCN mediated anti-inflammatory response, CDKN2A mediated ion-channel transport and ZBP1 mediated leishmania-infection." (PMID 37878133, 2023). "The level of the epigenetic marker at the position of genes WNT10A, JUNB, FOSL2, TNFAIP3, KLF4 and EDN1 was increased, and decreased at the position of genes MYCN and PCSK9, as was demonstrated by using the in vitro HCV-infection systems." (PMID 31216276, 2019). "We used the SK-N-SH cell line with a low MYCN level in this study and knocked down the PRMT1 expression via lentiviral shRNA infection." (PMID 30741995, 2019).
adenocarcinoma (9 papers, 2015 to 2025). A common cancer characterized by the presence of malignant glandular cells. "Further, it is shown that defined histone methylation (H3K4me3 and H3K27me3) landscapes emerged when the LNCaP adenocarcinoma cell line was engineered to overexpress MYCN, a known NEPC-related transcription factor." (PMID 40832297, 2025). "MYCN and its binding partner AURKA have been shown to play an important role in NEPC, and MYCN is overexpressed in a subset of CRPC adenocarcinomas (CRPC-Adeno)." (PMID 30652111, 2018).
CNS tumor (7 papers, 2013 to 2024). "Adult CNS tumours have high CDK6 amplification, 10q loss, and 17q gain, whereas paediatric cases have a high frequency and high specificity of 3q and 4q losses across MYC/MYCN oncogene amplification, suggesting variations in the chromosomal abnormalities between adult and paediatric CNS tumours." (PMID 39439908, 2024). "Spinal ependymoma, MYCN-amplified is a rare spinal ependymal tumor that has been recently characterized and included as a new entity in the 2021 WHO Classification of CNS Tumors (WHO Classification of Tumours Editorial Board, 2021)." (PMID 38544524, 2024).
hematological malignancies (5 papers, 2009 to 2021). "A number of evidences accumulated showing that the Myc protein (encoded by the main members of Myc family—MYCC and MYCN) plays a major role in hematopoiesis and hematologic malignancies." (PMID 23554972, 2013). "MYCN (N-myc) proto-oncogene is upregulated in many types of hematological malignancies including 20 to 40% of pediatric AML patients." (PMID 31412687, 2019).
nervous system tumors (5 papers, 2010 to 2020). "MYCN is a member of the MYC family of oncoproteins frequently amplified or overexpressed in aggressive, paediatric tumours of the nervous system." (PMID 21304178, 2010).
digestive system tumors (2 papers, 2020 to 2023). "Oncogene MYCN has been testified to play a critical regulatory role in many digestive system tumors." (PMID 32857725, 2020).
pituitary gland (1 paper, 2023). "Mice carrying only the MYCN transgene (hGFAP-cre::lsl-MYCN) show pancreas and pituitary gland tumors derived from neuroendocrine hGFAP-expressing cells in the two organs." (PMID 37407554, 2023).
MYCN also shares sentences with these, for which no sentence is quoted: Burkitt lymphoma (12 papers); T-cell acute lymphoblastic leukemia (9); cervical carcinoma (4); Intellectual disability (4); cerebellar tumor (3); Chronic Myelogenous Leukaemia (3); esophageal cancer (3); ganglioneuroma (3); nasopharyngeal carcinoma (3); neuronal tumor (3); pancreatic ductal adenocarcinoma (3); rhabdoid tumor (3); adrenocortical cancer (2); anaplastic thyroid carcinoma (2); Ataxia (2); atypical teratoid rhabdoid tumor (2); B cell chronic lymphocytic leukaemia (2); breast invasive carcinoma (2); clear cell renal cell carcinoma (2); esophageal squamous cell carcinoma (2); Fanconi anemia (2); glioneuronal tumor (2); head and neck squamous cell carcinoma (2); hematologic cancer (2); intestinal atresia (2); lung squamous cell carcinoma (2); malignant glioma (2); mantle cell lymphoma (2); megalencephaly (2); metastasis (2).
A further 91 diseases each share a sentence with MYCN in 2 papers or fewer.